IL6 (interleukin 6)
Diseases named in the same sentence as IL6 in open-access papers (continued):
Sharing a sentence is not in itself a finding about the gene and the disease.
asthma (continued). "The implications of elevated levels of serum IL‐6 on asthma control are not fully understood." (PMID 35811337, 2022). "Another study found that miR-3934 levels in PBMCs and serum can distinguish asthma patients from controls, particularly severe asthma patients, and that miR-3934 levels in PBMCs were negatively correlated with serum levels of IL-6, IL-8, and IL-33 in asthma patients, respectively." (PMID 36459329, 2022). "By comparing the blood samples of asthmatic patients with and without nocturnal symptoms between 4–5 A.M., we found that the expression of IL-6 in patients with nocturnal asthma attacks was significantly higher than that in asthmatic patients without nocturnal symptoms." (PMID 36505412, 2022). "Neutrophils are the main source of IL-6 generated in the airways of asthmatic patients and increased levels of IL-6 have been found in the sputum, serum, and bronchoalveolar fluid of asthmatic patients, especially in those with severe asthma." (PMID 35055456, 2022). "IL-6 binds to sIL-6R and activates the membrane-bound glycoprotein 130 (gp130), then actives Jak/signal transducer and activator of transcription (STAT) signaling pathway, which is implicated in a variety of inflammatory processes, including IPF and asthma." (PMID 35672815, 2022). "Compared with the model group, Danlong Dingchuan Decoction effectively reduced the expression levels of TNF-α, IL-4, TGF-β1, IL-6, IL-8, and IL-1β in the lung tissue, reduced the release of inflammatory factors, alleviated airway inflammatory response, and relieved asthma symptoms." (PMID 35186104, 2022). "It is possible that children with frequent exacerbations and high IL6 levels may grow up to be adults with severe asthma." (PMID 36140412, 2022). "Numerous previous studies have shown that eosinophilic asthma is mainly characterized by IgE and Th2 cytokines (IL-4, IL-5, etc.), whereas neutrophil asthma is mainly characterized by Th17 cytokines (IL-17, IL-6, etc.), which are involved in the development of steroid-resistant asthma." (PMID 36081945, 2022). "In the current study, we hypothesized that combined IL-6/TNF inhibition may be beneficial in the context of severe asthma." (PMID 35408882, 2022). "Interestingly, TNF blockade reduced IgE production to the level observed in mice with combined IL-6/TNF inhibition indicating a potential role for TNF-mediated signaling in modulation of the B-cell compartment in asthma." (PMID 35408882, 2022). "Interestingly, FP alone significantly reduced several pro-inflammatory genes related to ASM and asthma, including IL-6, MMP1, PTGS2, and TNFSF15." (PMID 35578269, 2022). "High blood levels of IL-6 were reported as a biomarker of asthma exacerbation." (PMID 36105239, 2022). "Targeting IL-5 and IL-6 pathways are research hotspots in the treatment of asthma." (PMID 36520525, 2022). "Treatment of bronchial smooth muscle cells (BSMCs) with the culture media (CM) of BEAS-NP and HBE-NP induced the expression of inflammatory cytokines IL-6 and IL-8, subsequently inducing their proliferation and migration; these are major features involved in asthma remodeling." (PMID 35010832, 2022). "Moreover, simultaneous administration of IL-6 and TNF inhibitors more effectively protects the lungs from asthma-associated tissue remodeling." (PMID 35408882, 2022). "Altogether, we concluded that combined inhibition of TNF and IL-6 more effectively reduces the inflammatory response in the lungs as compared to neutralization of these cytokines individually in acute HDM-induced mouse model of asthma." (PMID 35408882, 2022). "This suggests that the disorder of circadian clock genes and low expression of BMAL1 may lead to an increase in cytokines such as IL-6 and induce nocturnal asthma symptoms." (PMID 36505412, 2022). "As the JAK2/STAT3 pathway is preferentially activated by IL-6, prevention of IL-6/JAK2/STAT3 signaling may be associated with the anti-inflammatory effects of H. cuspidatus treatment of asthma." (PMID 35572723, 2022).
asthma (continued). "Key players of inflammatory response in asthma are Th2 and type 2 innate lymphoid cells, which produce IL-4, IL-5, IL-6, IL-9, IL-13, and IL-17E, resulting in overt immunoglobulin E (IgE) production, eosinophil accumulation, and inhibition of phagocyte-independent inflammation." (PMID 35681424, 2022). "Furthermore, analysis of human bronchial tissue samples supported the involvement of IL-6 in airway remodeling during asthma." (PMID 35408882, 2022). "Increased leptin and IL-6 levels in asthma patients have recently been identified in several studies, strengthening the link of these pro-inflammatory cytokines with airway inflammation in asthma." (PMID 34921631, 2021). "Thus, epithelial IL-6 signal transduction defines a novel asthma phenotype with increased airway inflammation." (PMID 34402724, 2021). "Finally, the levels of miR-3934 in PBMCs were negatively correlated with the serum levels of IL-6, IL-8, and IL-33 in asthma patients, respectively." (PMID 33506046, 2021). "Knockdown of IL-6 in macrophages could markedly reduce the levels of key indicators in type 2 allergic inflammation, and the inactivation of IL-6 played a protective role in asthma mice." (PMID 34608825, 2021). "In addition, PBNs obtained from patients with severe asthma were found to induce increased production of IL-1β, IL-6, and IL-8 in response to LPS plus S100A9, which further activated macrophages and AECs." (PMID 34285336, 2021). "We further demonstrated that asthma risk allele (C) of rs4792901 was associated with increased levels of serum IL6 in non-asthmatic healthy adults." (PMID 34552174, 2021). "Furosemide decreased the concentration of TNFα in SARS-CoV-2 infected patients, and together with IL-6 in the pre-eclamptic placenta, children with mild asthma, patients with respiratory disorders, patients with urosepsis, or patients with acute decompensated heart failure." (PMID 34768805, 2021). "Besides, IL-4 and IL-6 secreted by Th2 cells directly induce the generation of asthma-specific lgG1 and lgE, thus intensifying Th2 differentiation and regulating Th1/Th2 dynamic balance." (PMID 34630778, 2021). "As a specific marker of non‐T2 asthma, high plasma IL‐6 might be a potential therapeutic target in these asthmatics compared with other endotypes." (PMID 34194525, 2021). "Preliminary data suggests that combined pharmacological inhibition of TNF and IL-6 during asthma may be more efficient as compared to individual neutralization of these cytokines." (PMID 34084159, 2021). "Our paper shows that IL-6 in asthma exacerbates asthma symptoms by inducing ferroptosis." (PMID 34402724, 2021). "In addition to IL-6, soluble IL-6 receptor (sIL-6R) levels have consistently been elevated in children and adults with asthma." (PMID 33925531, 2021). "Moreover, MDD has been shown to stimulate the production of cytokines, including IL-13 and IL-6, both of which are also strongly involved in asthma pathogenesis." (PMID 34566951, 2021). "Previous studies have identified IL-17, IL-8, and IL-6 as key cytokines in non-T2 asthma." (PMID 34639020, 2021). "IL-6 levels showed an increase in asthma patients, which could facilitate migration of airway epithelial cell through regulating Akt/ glycogen synthase kinase 3 β signals." (PMID 34608825, 2021). "Moreover, asthma outcomes were significantly worse in obese IL-6-high asthma than in obese IL-6-low asthma." (PMID 33418879, 2021). "Asthma is characterized by chronic inflammatory infiltration caused by inflammatory cells and immune cells, and inhibition of TNF-α, IL-1β, IL-17, IL-4, and IL-6 contributes to improving asthma." (PMID 35069542, 2021). "IL-6, well known biomarker for asthma, increased nocturnally secretion in insomnia patients." (PMID 34750467, 2021). "Second, the small sample size of patients with moderate-to-severe asthma precluded us from robustly examining this specific group that may benefit more from anti-IL-6 therapies." (PMID 33912579, 2021).
asthma (continued). "Due to the advance in the airway inflammation hypothesis, the imbalance of Th17/Treg ratio has become a paradigm in asthma pathogenesis, and can affect a series of inflammatory cytokines, such as IL-6, IL-23, IL-17 and TGF-β." (PMID 33645621, 2021). "Experimental asthma models also demonstrated that IL-6R inhibitors attenuate the airway inflammatory response characterized by mixed granulocytic infiltration with elevated IL-6 and IL-6R levels." (PMID 33912579, 2021). "However, when applying the FDR correction for multiple testing, only IL-6 remained significant in asthma patients and 39 proteins remained significant in COPD patients." (PMID 34335580, 2021). "An interesting speculation is that children presenting frequent exacerbations and lower IL-6 levels may become adults with severe asthma phenotype." (PMID 33925009, 2021). "In addition, siRNA-based knock-down of ETV4 in an airway epithelial cell line model has demonstrated a significant reduction of cytokine expression relevant to asthma, including IL6 and IL8." (PMID 34552174, 2021). "Blood IL-6 has been recently identified as an interesting biomarker of asthma in adults." (PMID 33925009, 2021). "Ghrelin is expected to have anti-inflammatory actions that might suppress proinflammatory cytokines such as tumor necrosis factor (TNF)-α, IL-1β and IL-6, which are involved in the inflammation and pathogenesis of asthma." (PMID 32143340, 2020). "MK2 and 3 are kinases activated by p38α; MK2/3 inhibitors or knockout of MK2/3 in mice reduced the production of IL-6 and IL-13 (two cytokines implicated in asthma) but not IL-5, IL-9 or GM-CSF in response to IL-33." (PMID 32103032, 2020). "TNF-α and IL-6 are major pro-inflammatory cytokines involved in asthma." (PMID 32929606, 2020). "To demonstrate the potential of our approach, we first used it to analyze bronchoalveolar lavage fluid (BALF) samples from patients with mild-to-severe asthma, and found that patients with asthma had higher levels of GN bacteria and IL-6 than healthy control subjects." (PMID 32451375, 2020). "SIRT1 regulated IL-6 expression in the ovalbumin-induced asthma mouse model." (PMID 32823491, 2020). "Collectively, MEO may have an inhibitory effect on asthma under the condition of PM10 exposure through the IL-6/JAK2/STAT3 signaling pathway." (PMID 33374928, 2020). "Peppermint oil would help to alleviate asthma by inhibiting the IL-6/JAK2/STAT3 pathway." (PMID 33374928, 2020). "Acupuncture can remarkably decrease IL-6 and IL-10 in asthma patients." (PMID 33144870, 2020). "The level of pro-inflammatory cytokine IL-6 was elevated in asthma patients." (PMID 32624703, 2020). "Interestingly, IL-6 trans-signaling is associated to risk of future cardiovascular events and recently, epithelial IL-6 trans-signaling has been shown to define a new asthma phenotype with increased airway inflammation." (PMID 32194407, 2020). "Moreover, astaxanthin reduced the production of pro-inflammatory mediators and cytokines such as nuclear factor-κB (NF-κB), tumor necrosis factor-α (TNF-α), and interleukin-6 (IL-6), and suppresses T lymphocyte activation in asthma patients." (PMID 33374738, 2020). "In fact, the increment of IFN-γ/IL-6 ratio indicated the increased Th1/Th2 balance which could be of therapeutic value in inflammatory conditions such as asthma and cancer." (PMID 32995329, 2020). "Besides being present as an immune modulator in various lung diseases, IL-6 has also been suggested to play a role in pathogenesis of asthma and COPD." (PMID 33147273, 2020). "The expression of IL-6 in asthma patients is significantly increased." (PMID 31790411, 2019). "The level of IL-6 in asthma patients is substantially higher than in normal persons." (PMID 31790411, 2019). "It is worth to report that higher levels of IL-6 are presented in different airway diseases in which a Th2 immune response is associated, such as allergic, chronic obstructive pulmonary disease (COPD), and asthma." (PMID 31726719, 2019).
asthma (continued). "In this study, we performed a proof‐of‐concept clinical trial to test the hypothesis that a drug that blocks both IL‐6 classic signalling and trans‐signalling can be used to prevent allergen‐induced asthma exacerbations." (PMID 31223480, 2019). "Release of interleukin-1β (IL-1β), and Il-6, as a pro-inflamatory stimulating cytokine, could be reduced significantly by SalA60, also in neutrophils in in vivo asthma mouse model." (PMID 31594975, 2019). "This IL-6 driven immune-senescence may serve as part of a feed forward loop that drives asthma progression and reduces the efficacy of anti-inflammatory treatments." (PMID 31849968, 2019). "PheWAS and MR analyses also unraveled a protective role for IL6 signaling in AD and asthma." (PMID 31552141, 2019). "Additionally, a study of Massoud and colleagues showed that IL-4 and IL-6 are involved in converting induced regulatory T (Treg) cells into TH-17 like cells, therefore potentially contributing to asthma severity." (PMID 31640701, 2019). "Interestingly, although IL‐27 production was increased in the IfitmF–/– mice compared to WT in our asthma experiments, levels of Il4, IL‐5, IL‐13, IL‐6, IL‐10, IL17, and TNF‐α were all decreased." (PMID 30365177, 2019). "There is emerging evidence implicating IL-6 and its receptor in the pathogenesis of asthma." (PMID 31395050, 2019). "Therefore, reduction of CD126 expression in monocytes, neutrophils, and CD4+ cells from moderate-severe patients highlights the role of IL-6 trans-signalling in asthma severity." (PMID 31101830, 2019). "Th17-related cytokines such as TNF-α, IL-6, and IL-1β are important in the control of asthma onset." (PMID 31790411, 2019). "In a study of two adult cohorts, plasma IL-6 was measured as a marker of systemic inflammation and related to BMI and asthma outcomes Patients who were IL-6 high were more likely (but not inevitably) obese, and had worse FEV1 and more likely a history of asthma attacks." (PMID 30941334, 2019). "IL-6 is increased in patients with asthma and is especially increased during asthma attacks." (PMID 30485264, 2018). "Pharmacological blockade of IL-6 results in the reduction of airway inflammation in some asthma models, suggesting that this cytokine may be driving several types of responses to the allergen." (PMID 30534125, 2018). "In addition, an impairment of the DC maturation and migration from the lungto-draining lymph nodes as well as IL-12 and IL-6 secretion was observed, which resulted in reduced Th1 and Th17 cell responses that are predominant in this asthma model." (PMID 29967803, 2018). "There is interest in a role of IL-1β as inducer of IL-17 and IL-6 in asthma." (PMID 29361942, 2018). "Similarly, our previous study revealed that ambient PM strongly induces neutrophilic airway inflammation through macrophage inflammatory protein (MIP)-2 (MIP-2/CXCL2), which is a murine homologue of IL-8, and IL-6 in a mouse model of asthma." (PMID 29882826, 2018). "The suppressive effect of IL-6 release stimulated by LPS from monocytes might be beneficial in the context of asthma as it is considered a pro-inflammatory mediator and found in high serum levels of patients with asthma." (PMID 30333747, 2018). "IL-6 expression was increased in bronchial epithelial cells of patients with asthma." (PMID 30333747, 2018). "Some serum biomarkers like interleukin-6 (IL-6), interleukin-8 (IL-8) and monocyte chemoattractant protein-1 (MCP-1) have been found to be associated with airway inflammation in obstructive lung diseases, including COPD, asthma and bronchiectasis." (PMID 29548305, 2018). "This study investigated the activity of distinct NS preparations on asthma-related targets such as the release of IL-2, IL-6, and PGE2 from peripheral mononuclear human blood cells and a human epithelial cell line (A549) to provide the basis of a clinical study." (PMID 30333747, 2018).
asthma (continued). "Interestingly, at steady state conditions, most of the IL-6 producing cells were represented by macrophages and monocytes (i.e., myeloid cells), whereas after the induction of asthma, the contribution of the T cell fraction increased." (PMID 30534125, 2018). "In patients with asthma, IL-6 was found at a high level in serum as well as in BALF." (PMID 30333747, 2018). "However, the percentage and fluorescence intensity of the IL-6-expressing lymphoid cell population remained significantly higher following asthma induction." (PMID 30534125, 2018). "The purpose of this study was to explore the associations of interleukin-4 (IL-4), IL-6, and IL-12 levels in peripheral blood (PB) with lung function, cellular immune function, and children's quality of life (QOL) with moderate-to-severe asthma." (PMID 28328807, 2017). "Therefore, it is likely that the increased IL-6 response in RSV patients with wheezing would provide a substratum for the development of subsequent asthma, resulting in more significant changes related to asthma, especially in children with LBW." (PMID 29246125, 2017). "IL-6 is an important factor that regulates asthma induction via CD4+ cell modulation." (PMID 29151835, 2017). "High levels of IL-4 and IL-6 and low levels of IL-12 were apparent in asthma patients, while IL-4, IL-6, and IL-12 might be associated with lung function and QOL of asthma patients." (PMID 28328807, 2017). "In the present study, increased serum IL-6 levels in infants with LBW might also play an important role in RSV induced wheezing or asthma." (PMID 29246125, 2017). "Based on this finding, we hypothesized that a hypercoagulable state in asthma is related to the systemic inflammatory response largely mediated by interleukin (IL)-6, which is the most important inducer of the synthesis of acute phase proteins, including CRP." (PMID 28429138, 2017). "IL-6 signals via two types of receptors: membrane-bound IL-6 receptor (mIL-6R) and circulating soluble receptor (sIL-6R), and the use of these receptors can profoundly influence asthma pathogenesis." (PMID 29118754, 2017). "Therefore, we investigated the associations between the previously analyzed parameters of a prothrombotic state in asthma and concentrations of IL-6 and TNFα and periostin in peripheral venous blood." (PMID 28429138, 2017). "Asthma was characterized by 62% higher plasma IL-6 and 35% higher TNFα (both, p < 0.0001)." (PMID 28429138, 2017). "IL‐6 is known to be a potential contributor of asthma pathogenesis." (PMID 28474507, 2017). "IL-6 levels probably reflect an activated state of the lung, and may have a role as a biomarker for asthma." (PMID 29246125, 2017). "Besides IL-17, IL-6 has been considered as promising target to reduce pathogenesis of asthma and COPD, particularly those of eosinophilic/neutrophilic phenotype." (PMID 29184554, 2017). "Our study demonstrates that enhanced thrombin generation in asthma might be a reason of systemic inflammatory state and is, at least partially, driven by inflammatory cytokines, such as IL-6 and TNFα." (PMID 28429138, 2017). "Further in vivo study is needed to clarify the importance of the IL‐17F/IL‐6 axis in asthma." (PMID 28474507, 2017). "Increased viral replication was associated with enhanced IL‐6 and IL‐8 production during RV14 infection in the present study, and this effect may be also associated with the development of asthma exacerbations during RV infection." (PMID 27957326, 2016). "Given that obese patients with asthma are less sensitive to treatment with steroids either Th2/Th17 or Th17 induction by IL-6 may play a significant role in the disease process." (PMID 27212806, 2016). "On the other hand, ELISA results also demonstrated that expression of IL-4, IL-6, and IL-17a was reduced when compared with asthma induced mice and further confirmed that the inflammation response could be inhibited by Nepeta bracteata Benth." (PMID 27073403, 2016).